CLLU1-AS1 (CLLU1 antisense RNA 1)
Synonyms: CLLU1OS
Gene: Long non-coding RNA gene on chromosome 12 (92,420,091 to 92,433,060, reverse strand). Ensembl gene ENSG00000205057.
Diseases named in the same sentence as CLLU1-AS1 in open-access papers:
CLLU1-AS1 is named in the same sentence as 4 diseases in open-access papers, as found by Europe PMC text mining. Sharing a sentence is not in itself a finding about the gene and the disease.
CLLU1-AS1 shares sentences with these, for which no sentence is quoted: glioma (1 paper); prostate adenocarcinoma (1); prostate carcinoma (1); tumor (1).